AXIN2 (axin 2)
Diseases named in the same sentence as AXIN2 in open-access papers (continued):
Sharing a sentence is not in itself a finding about the gene and the disease.
cancer (continued). "Relative expression level showed that stromal fibroblasts from both normal and cancer donors promoted upregulation of stemness-related genes (ALDH1, AXIN2, CD133, MYC, and SOX9) in EEC organoids." (PMID 36273006, 2022). "Further, treatment with EC359 reduced the spheroid formation of EC cancer stem cells and reduced the levels of cancer stem cell markers SOX2, OCT4, NANOG, and Axin2." (PMID 34400617, 2021). "Immunohistochemical staining was performed for AXIN2, MYBL2, TGFBI, and SLC35D3, which represented that the part of cancer was deeper than that of normal." (PMID 35174154, 2021). "Interestingly, mutations in the AXIN2, MSX1, PAX9, and WNT10A genes may be associated with cancers." (PMID 34378652, 2021). "Therefore, the AXIN2 mutations could lead to an inefficient block of the WNT signaling pathway and altered the embryonic development of dental organs and predisposition to cancer." (PMID 33732167, 2021). "Accordingly, depletion of Sec62 decreased the expression of Wnt target genes including AXIN2, LGR5 and MYC, all of which play critical roles in maintaining cancer cell stemness and CRC progression." (PMID 33858476, 2021). "Among the validated gene targets of both miR-194-5p and miR-374a-5p, we also found CCND2, AXIN2, and BMPR2, regulated by the Hippo signaling pathway, involved in stemness and cancer biology." (PMID 34828332, 2021). "Axis inhibition protein 2 (Axin2), a scaffolding protein of glycogen synthase kinase 3 (GSK-3), promotes cancer cell invasion and metastasis in various types of malignancies by inhibiting GSK-3-mediated Snail degradation." (PMID 33046030, 2020). "We also inferred that AXIN2 probably regulates the cell differentiation of T cells CD8 and T cells CD4 memory resting through the WNT pathway, subsequently influencing cancer prognoses." (PMID 31681739, 2019). "Among the KEGG-annotated pathways regulating stem cell pluripotency and pathways in cancer, several stem cell regulatory transcripts modulated by ADAR111, including AXIN2, MAPK3, and FGFR3, were enriched." (PMID 29203771, 2017). "This study suggests a new regulatory mechanism of SFRP1, AXIN2, and ICAT, and also implies that the three genes play a significant role in mediating cancer stemness." (PMID 26337084, 2015). "We first tested the effects of RBM47 on cancer cell Wnt responsiveness by treating WT6 cells with recombinant Wnt3A and subsequently measuring the expression of AXIN2, a common TCF/β-catenin target gene and a general marker of Wnt activity." (PMID 24898756, 2014). "We measured the abundance of the corresponding AXIN2 mRNA in the original SSAs and MSI cancers (Group 2) by quantitative reverse transcription–polymerase chain reaction (RT–PCR)." (PMID 24964857, 2014). "They identified several genes (AXIN2, MSX1, PAX9, WNT10A, EDA, BARX, and BRCA1) that may play a role in both hypodontia and cancer development." (PMID 38523193, 2024). "We found that high CCNP expression correlated with a high expression of Axin2 (p < 0.0001), cyclin D1 (CCND1) (p = 0.0026), Lgr5 (p < 0.0001) and Ascl2 (p < 0.0001), suggesting that CCNP and stemness are broadly intertwined in human cancer." (PMID 34604945, 2021). "Finally, we found that in various types of cancer, the levels of TFEB mediated Wnt target genes exhibit strong correlations with the level of Axin2, which represents the activity of Wnt signaling." (PMID 33753903, 2021). "Moreover, the transcription factor CUX1, by targeting key subunits of the Wnt/β-Catenin pathway, showed a positive correlation with mRNA expression of Axin2, CTNNB1, and TCF4 in most normal and cancer tissues or cell lines." (PMID 34422906, 2021).
cancer (continued). "In the present study, Axin2 expression was found in the cytoplasm of cancer cells in 168 (77.4%) patients with OSCC, and immunoreactivity against Axin2 was high in 101 (high-Axin2, 46.5%) OSCC tissue samples and low in 116 (low-Axin2, 53.5%)." (PMID 33046030, 2020). "Similar to Axin2, the roles of GSK3 in various cancers are controversial." (PMID 32486158, 2020). "Some of them were reported to be cancer-related genes, such as CCNB1, EZH2, AXIN2, and FOXF2." (PMID 31321712, 2019). "Axin2, a GSK3 scaffolding protein, plays a key regulatory function in this process by regulating nuclear-cytoplasmic shuttling of GSK3, resulting in increased nuclear Snail in cancer cells." (PMID 28418862, 2017). "In this study we identify Notum as a potential biomarker for Wnt driven cancers and show that coordinate regulation of NOTUM and AXIN2 expression may be a useful predictor of response to PORCN inhibitors." (PMID 26848981, 2016). "In all Axin2+/lacZ mice fibroblast like cells surrounding the carcinoma did not express β-galactosidase." (PMID 27555909, 2016). "Further, we also found the down regulation of anti-apoptotic molecules BCL-2, Bcl-xL, cIAP2, XIAP, Axin2 and Survivin in the AKAP4-depleted CRC cells indicating that AKAP4 may be potential therapeutic target in cancer management." (PMID 26590805, 2015). "We also detected a correlation between β-catenin as shown by western blots against the active form of β-catenin dephosphorylated on Ser37 or Thr41 and the downstream effector Axin 2 and MGMT expression in the majority of cancer cell lines derived from these cancers." (PMID 26603103, 2015). "The dysregulation of SFRP1, AXIN2, and ICAT has been largely reported in numerous types of cancers." (PMID 26337084, 2015). "Wnt signaling participates in many processes during embryonic development and cancer progression; it exerts its effects through activation of the β-catenin/TCF transcription complex and expression of downstream genes, such as CyclinD1 and Axin2." (PMID 24466042, 2014). "Many of those more frequent in BRAFmut/MSS cancers, for example deletions at 6p25.1-6p21.33 and at specific loci on 17q where several Wnt regulatory genes reside (RNF43, AXIN2 and SOX9), have not commonly been associated with CRC." (PMID 24651849, 2014). "In addition, six of the frequently hypermethylated genes, i.e., CCND1, COL4A2, HDAC2, AXIN2, ABL1 and GLI2, are included in the pathways in cancer map from the KEGG database." (PMID 22159500, 2012). "In addition, the expression of c-myc and axin-2, established downstream targets of β-catenin, were also significantly reduced in these CRT-positive cancer cells following incubation with CGK062." (PMID 23071615, 2012). "AXIN2 overexpression under hypoxic conditions was shown to exhibit an opposite effect to miR-1275 overexpression, i.e. AXIN2 overexpression was able to inhibit perforin, IFN-γ and TNF-α secreted by NK-92 cells after incubated with Panc-1 and inhibited the ability of NK-92 cells to kill cancer cells." (PMID 38035113, 2023). "Axis inhibition protein 2 (AXIN2), which can suppress GSK3 activity and destruction complex formation and ultimately inhibit β-catenin, is involved in the regulation of cell proliferation, invasion, migration, metastasis and other functions in a variety of cancers." (PMID 35819532, 2022). "Consistent with those anti-cancer effects, several groups have reported that niclosamide suppresses β-catenin mediated canonical Wnt signaling, through means such as inhibited TCF/LEF transcriptional activity and down-regulated pathway target genes, e.g., Axin2." (PMID 34298652, 2021). "Interestingly, Metformin had no inhibiting effect on SOX4 and AXIN2 levels in non-cancer cell lines (HEK293T, MRC5, and C2C12)." (PMID 29977599, 2018).
cancer (continued). "These cancers, through their heavily methylated phenotype have been found to methylate other inhibitors of the Wnt pathway such as DKK1 and AXIN2, which indicates epigenetic regulation of the Wnt pathway may be more prevalent in the BRAF mutant/MSI compared to other CRC subtypes." (PMID 25613750, 2015). "It is of note that induction of replication stress by aphidicolin or alleviation of endogenous replication stress in CIN+ cancer cells by deoxynucleoside treatment did not influence canonical Wnt signaling as determined by the expression of the well-established β-catenin/TCF target gene AXIN2." (PMID 40846632, 2025).
infection (16 papers, 2010 to 2025). The state of being infected such as from the introduction of a foreign agent such as serum, vaccine, antigenic substance or organism. "This factor is indeed present at increased levels upon infection, driving an expansion of Axin2+ stem cells." (PMID 31248166, 2019). "Axin2, a well-established direct target of β-catenin, was up-regulated by 40 to 70-fold in cells at 72 h post-infection across all GOF samples further demonstrating successful excision of Ctnnb1 Exon 3 and activation of the pathway." (PMID 29209359, 2017). "Infection with H. pylori as well as treatment with recombinant Wnt3a, but not heat-killed H. pylori strongly induced protein expression of Axin2." (PMID 20137080, 2010). "In this context, infection with H. pylori has been shown to interfere with the homeostatic division of stem cells within the antral gland, resulting in an increased number and division rate of Axin2+ cells." (PMID 31248166, 2019). "In the present study, low levels of β-catenin/Wnt signalling at the peak of infection may have been the result of the enhanced expression of AXIN2 and SOX9, observed in crypts at 7 and 14 dpc." (PMID 28323899, 2017). "Upregulation of the well-established Wnt target gene Axin2 could be detected as soon as 3 h post infection." (PMID 20137080, 2010). "The upregulation of the Wnt target gene expression, including Axin2, EPHB2, CCND1, CD44, TERT, and MYC in PEDV-infected cells, further highlights the activation of WNT signaling in response to infection." (PMID 40396761, 2025). "Lentiviral infection efficiency was assessed by red fluorescent protein (RFP) signal intensity co-expressed by the same bicistronic vector, and AXIN2 mRNA levels were determined by qRT-PCR." (PMID 26905812, 2016). "The results showed an increase in the proportion of stem cells in the S and G2/M phases, upregulation of proliferation-related genes, and activation of the Wnt pathway, evidenced by the elevated expression of Wnt target genes such as AXIN2, EPHB2, CCND1, CD44, TERT, and MYC following infection." (PMID 40396761, 2025). "Our results showing transcriptional upregulation of AXIN2 suggest the activation of this negative feedback loop during infection with Jad/C(1aCvar) and Jad/C(4fC)." (PMID 30046100, 2018). "We found that infection with Jad/C(4fC) resulted in the significant upregulation of c-MYC (P < 4 × 10−6), TBX3 (P < 0.0006), AXIN2 (P < 0.0068), FNDC3B (P < 1 × 10−5), FASN (P < 0.0005) and CCND1 (P < 0.0002), with c-MYC and TBX3 showing the highest upregulation levels." (PMID 30046100, 2018). "Although the mRNA transcript levels of Wnt3 and Axin2 in mouse intestinal organoids were not significantly altered after infection with H9N2 virus for 1 or 12 h, the expression level of Wnt3 was significantly reduced at 48 h." (PMID 29096712, 2017). "Expression of p63 and Axin2 then decreased at 5 to 7 d post-infection, regardless of whether the cells were incubated in 50% or 5% CM at day 3 post-infection, showing that either extended culture or lower CM percentage can reduce Wnt signalling." (PMID 37037942, 2023).
adenocarcinoma (3 papers, 2007 to 2015). A common cancer characterized by the presence of malignant glandular cells. "Gene expression of LEF1 and AXIN2 were correlated in the microarray dataset of the adenocarcinoma brain metastases." (PMID 23224985, 2013). "In addition to the expected up-regulation of AXIN2, which is widely accepted to be an important downstream effector of the Wnt signaling cascade, a high number of other important targets and members of the Wnt signaling pathway were differentially expressed in adenocarcinoma." (PMID 26517809, 2015).
infectious disease (1 paper, 2012). A disorder directly resulting from the presence and activity of a microbial, viral, or parasitic agent in humans. "The results suggest a distinct biological function of Axin1 and Axin2 in infectious disease and intestinal inflammation while they are functionally equivalent in developmental settings." (PMID 22509369, 2012).
AXIN2 also shares sentences with these, for which no sentence is quoted: Hypodontia (17 papers); cleft palate (4); leukoplakia (3); papillary thyroid cancer (3); diabetes (2); endometrioid ovarian adenocarcinoma (2); gastric polyps (2); genetic disorder (2); incontinentia pigmenti (2); Insulin resistance (2); malignant peripheral nerve sheath tumor (2); oral squamous cell carcinoma (2); osteoporosis (2); periodontal disease (2); polyposis (2); Allergy (1); ampullary carcinoma (1); anaplastic cancer (1); Anxiety (1); astrocytoma (1); autism (1); autism spectrum disorder (1); B-cell non-Hodgkin lymphoma (1); basal cell nevus syndrome (1); blepharocheilodontic syndrome (1); breast adenocarcinoma (1); breast invasive carcinoma (1); bronchial hyperreactivity (1); Burkitt lymphoma (1); carcinoma of the digestive system (1).
A further 49 diseases each share a sentence with AXIN2 in 1 paper.